NF1 (neurofibromin 1)
Diseases named in the same sentence as NF1 in open-access papers (continued):
Sharing a sentence is not in itself a finding about the gene and the disease.
cardiac hypertrophy (6 papers, 2012 to 2025). "Mice with specific loss of NF1 in the heart developed marked cardiac hypertrophy in adult life, with progressive dilated cardiomyopathy and fibrosis." (PMID 34344467, 2021). "Mutations of Ras negative regulator NF1 are associated with characteristic neurofibromas (Schwann cells neoplasms) and cardiac hypertrophy." (PMID 34344467, 2021). "The cardiac-specific Nf1 knockout mice, combined with genetic rescue, suggest that neurofibromin is an important regulator of Ras signaling in cardiac myocytes, and that Ras activation can lead to progressive cardiac hypertrophy with associated pathological changes in adult mice." (PMID 23244495, 2012). "In addition, loss of function of Neurofibromatosis type I (NF1) and Shp2/PTPN11, two modulators of Alk associated Ras/Raf/ERK-signaling cause cardiac hypertrophy." (PMID 40382638, 2025). "However, the cardiac phenotype is only present among patients with large NF-1 deletions: a clinical study found that only 6 out of 16 patients with neurofibromatosis had congenital heart disease, and only three of them had cardiac hypertrophy." (PMID 34344467, 2021). "Notably, the selective inhibition of DUSP genes has been shown to promote cardiac development, while deletion of NF1 in neonatal mice leads to cardiac hypertrophy and premature mortality." (PMID 32730272, 2020).
cerebrovascular disease (6 papers, 2011 to 2022). "Because patients with NF-1 are at increased multiple risk of developing cerebrovascular diseases and benign or malignant tumors, early identification can help targeted examination, multidisciplinary management, and long-term clinical monitoring." (PMID 34988040, 2021). "Several NF-1 cases have been reported in children, but the incidence of cerebrovascular diseases (CVDs) associated with complications and the long-term impacts on NF-1 cases is still poorly recognized, which warrants more studies on the important topic." (PMID 33395412, 2021). "Although not commonly recognized in the context of NF-1, cerebrovascular disease (CVD), can be often present since childhood and diagnosed just later in life." (PMID 33395412, 2021).
colon adenocarcinoma (6 papers, 2011 to 2025). "A case of synchronous multiple colon adenocarcinomas in a patient with NF1 was also reported." (PMID 28835241, 2017). "As a result, NF‐1 treatment can convert “cold” tumors into “hot” tumors by reshaping the MIF‐mediated immunosuppressive network, NF‐1 treatment thus enabling effective immunotherapy in BRCA and enhancing the ICB efficacy in colon adenocarcinoma (COAD)." (PMID 39908165, 2025). "NF‐1 treatment‐induced MIF reduction can reshape the immunosuppressive network and convert a “cold” tumor into a “hot” tumor, thus enabling immunotherapy in BRCA and enhancing the ICB efficacy in colon adenocarcinoma (COAD)." (PMID 39908165, 2025). "We report a rare case of simultaneous NF1, GIST and colon adenocarcinoma." (PMID 31805970, 2019).
diffuse astrocytoma (6 papers, 2009 to 2025). A low-grade (WHO grade II) astrocytic neoplasm. "Additional somatic alterations included BRAF p.V600E mutation in the pleomorphic xanthoastrocytoma and PTPN11, ATRX, and NF1 mutations in the diffuse astrocytoma." (PMID 28699883, 2017). "In the diffuse astrocytoma, we show that the germline CDKN2A/B deletion was accompanied by somatic loss of the remaining CDKN2A/B alleles as well as an activating hotspot mutation in PTPN11 and inactivating frameshift mutations in the ATRX and NF1 tumor suppressor genes." (PMID 28699883, 2017). "The analysis of Stokland identified that fibrillary/diffuse astrocytoma had a significantly lower PFS rate, the cohort included treated and untreated as well as NF1 and non-NF1 patients." (PMID 28649001, 2017).
infantile spasms (6 papers, 2019 to 2025). A rare epilepsy syndrome characterized by onset of epileptic spasms in infants between 2 and 12 months of age, and rarely up to 24 months. "An association between NF1 and West’s syndrome was described in the literature with a favorable outcome or was followed by resistant seizures, which could not be controlled by polytherapy." (PMID 41225983, 2025). "Our result indicates that damaging NF1 variants can be an often overlooked but relatively frequent cause of EE/DEE, especially of infantile spasm." (PMID 31175295, 2019). "Among these nominally significant genes, we found exome-significant enrichment of damaging DNMs in NF1 in infantile spasm." (PMID 31175295, 2019). "These three individuals with a damaging DNM in NF1 did not harbor other variants that can explain infantile spasm." (PMID 31175295, 2019). "In addition, we note that all probands carrying a damaging DNM in NF1 were diagnosed with infantile spasm." (PMID 31175295, 2019).
juvenile xanthogranuloma (6 papers, 2012 to 2023). A benign histiocytic tumor that occurs during childhood; it is distinct from Langerhans cell histiocytosis. "Since JMML is rare in individuals with NF1, specific clinical assessment for JMML is not advised in children with NF1 and juvenile xanthogranulomas." (PMID 36684394, 2023).
lipoma (6 papers, 2012 to 2025). A benign, usually painless, well-circumscribed lipomatous tumor composed of adipose tissue. "Similarly, multiple spinal ganglioneuromas and multiple lipomas were reported in association with a pathogenic NF1 variant, without other clinical features of NF1." (PMID 37686284, 2023).
lymph node metastasis (6 papers, 2017 to 2022). "BRAF, RAS, and NF1 mutations were significantly associated with lymph node metastasis or presence of ulceration, implying that these cancer driver genes were independent prognostic factors." (PMID 32083130, 2020). "In the lymph node metastases/lymph node metastases-paired samples group, 6 gain-of-function mutations were observed with only one being pathogenic (APC), 1 VUS (NF1) and 4 unclassified." (PMID 34707195, 2021). "Based on the correlations between the driver gene (NF1, BRAF, and RAS) alterations and clinical characterizations (ulceration, lymph node metastasis), patients harboring more mutations were prone to poor prognosis." (PMID 32083130, 2020). "A 1.5-year-old girl (NF1 c.4110 + 2T > G (IVS30(+ 2)T > G)) had a germ cell tumor in the pelvic area with bone, lung, and lymph node metastasis." (PMID 35093157, 2022). "Similar to NF1 and/or BRAF subtypes, patients with lymph node metastasis and/or ulceration had more RAS mutations than those without lymph node metastasis or ulceration." (PMID 32083130, 2020).
mesothelioma (6 papers, 2014 to 2025). A usually malignant and aggressive neoplasm of the mesothelium which is often associated with exposure to asbestos. "Transcriptome profiling of NF1 mutant H2052 mesothelioma cells indicated that VT107 strongly represses the expression of many YAP/TEAD target genes in both parental and NF1 mutant cells, but the transcriptional response is blunted by NF1 loss." (PMID 39103676, 2024). "To validate our whole-genome screens, we used CRISPR/Cas9 mutagenesis with two independent sgRNAs to mutate NF1, SOCS3, and VGLL4 in H226 and H2052 cells, as well as a third mesothelioma cell line, MSTO-211H, which harbors inactivating mutations in both LATS1 and LATS2." (PMID 39103676, 2024).
myeloid leukemia (6 papers, 2011 to 2023). A clonal proliferation of myeloid cells and their precursors in the bone marrow, peripheral blood, and spleen. "Molecular investigations of myeloid leukemia cell lines revealed the presence of binding sites for ubiquitous (NF-1 and SP-1) and myeloid enriched (MZF-1-like protein, GATA-1, and Ets-1) transcription factors in the promoter region of the gene." (PMID 31709175, 2019). "Insertional inactivation of the NF-1 tumor suppressor gene has also been found in myeloid leukemias arising in BXH-2 recombinant inbred mice —the CIS originally termed evi-2 was found to be in the NF-1 gene." (PMID 21994739, 2011).
Osteopenia (6 papers, 2012 to 2024). Osteopenia is a term to define bone density that is not normal but also not as low as osteoporosis. "While focal bone defects (e.g. a tibial pseudarthrosis) are associated with double inactivation of NF1, it is likely that the systemic osteopenia seen in some NF1 individuals is due to haploinsufficiency." (PMID 38913608, 2024).
overgrowth syndrome (6 papers, 2019 to 2024). A group of syndromes caused by genetic birth defects that may lead to the development of malignancies. "RNF135 loss-of-function mutations, as well as an NF1-REPa to NF1-REPb deletion including this gene, have been implicated in an overgrowth syndrome which includes tall stature, macrocephaly, dysmorphic features, and variable additional features, including learning disability." (PMID 31652930, 2019). "In addition, both loss-of-function mutations of ring finger protein 135 (RNF135) and microdeletion of NF1-REPa to REPb including RNF135 contribute to an overgrowth syndrome including tall stature, macrocephaly, dysmorphic features, and variable additional features in NF1 patients." (PMID 34566848, 2021).
pancreatic endocrine tumors (6 papers, 2009 to 2024). "Interestingly, pancreatic endocrine tumors occur in patients with NF1 and have been reported to be a cause of death in these patients." (PMID 38874808, 2024). "It has been reported that GIST may co-exist with pancreatic endocrine tumors but this has only been in association with NF-1." (PMID 19216788, 2009). "Although there is a case report showing an association of NF1 with OS in pancreatic endocrine tumors, NF1 mutation in PDAC has not been reported in terms of clinical outcome." (PMID 34205170, 2021).
pediatric cancer (6 papers, 2018 to 2026). "As CNS tumors are the leading cause of pediatric cancer related death, managing these tumors in NF1 and NF2-SWN patients requires coordinated multidisciplinary life-long care." (PMID 41847710, 2026). "The analysis detected mutations in several cancer-related genes previously reported to be implicated in pediatric cancer, such as CTNNB1, WT1, AMER1, and NF1." (PMID 38672648, 2024).
pleomorphic liposarcoma (6 papers, 2011 to 2022). Pleomorphic liposarcoma (PLS), the rarest subtype of liposarcoma (LS), is an aggressive, fast growing tumor located usually in the deep soft tissues of the lower and upper extremities.
Rett syndrome (6 papers, 2017 to 2025). A severe neurodevelopmental disorder affecting the central nervous system. "The syndromic group (n = 6) comprised one patient each of Sotos syndrome (SS), Rett syndrome (RS), Prader Willi syndrome (PWS), Neurofibromatosis 1 (NF1), Andersen Tawil syndrome (ATS) and Pterygium syndrome (PS)." (PMID 34297320, 2021).
schizophrenia (6 papers, 2011 to 2023). A major psychotic disorder characterized by abnormalities in the perception or expression of reality. "Mesolimbic dopaminergic circuits are thought to play a role in the pathophysiology of several neuropsychiatric conditions, including disorders of impulse control, schizophrenia, and neurodevelopmental disorders, including NF1." (PMID 37067979, 2023).
Subcutaneous neurofibroma (6 papers, 2011 to 2025). A neurofibroma (benign peripheral nerve sheath tumor) localized in the subcutis (subcutaneous region). "NF1 microdeletions are often associated with a severe clinical phenotype, whereas the variant c.2970_2972del (p.Met992del) is associated with a mild phenotype lacking externally visible plexiform, cutaneous, or subcutaneous neurofibromas." (PMID 40410838, 2025). "NF1 c.5750-184_5750-178dup (GRCh37 chr17:29661671-C-CTTTCTTC) was identified in a child with multiple café-au-lait spots, suspected subcutaneous neurofibromas, axillary freckles and macrocephaly." (PMID 41300834, 2025).
thyroid cancer (6 papers, 2021 to 2025). "DriverML predicted that BRAF and NF1/PMS2 mutations are the main driving mutations in thyroid cancer, and they play a certain role in regulating its development." (PMID 35865459, 2022). "In the thyroid cancer samples BRAF mutations co-occurred less frequently than expected with mutations in NRAS, HRAS, RET, PTEN, NF1 and KRAS." (PMID 36275468, 2022). "Using a computer algorithm to identify major driver mechanisms in our PTC cohort, the results showed that, in addition to BRAF mutations, NF1, PMS2, CDC27 and PPP4R2 gene mutations are also involved in the development of thyroid cancer, and joint mutations often occur." (PMID 35865459, 2022). "In addition, we found that BRAF and NF1 mutations are two of the main regulators in Chinese PTC patients, and they play critical but different roles in regulating the development of thyroid cancer." (PMID 35865459, 2022). "Because BRAF and NF1/PMS2 have significant mutually exclusive relationship, we speculate that the mechanism of gene mutation leading to the occurrence and development of thyroid cancer may be different between the two groups." (PMID 35865459, 2022).
tumor syndrome (6 papers, 2012 to 2023). "Neurofibromatosis type 1 (Nf1) is a genetically determined neurodevelopmental disorder and tumor syndrome with an incidence of approximately 1/3000 live births." (PMID 37760547, 2023). "While NF1 is an autosomal-dominant (AD) inherited tumor syndrome, almost half of the time NF1 originates de novo in individuals with no known previous family history of NF1." (PMID 37181996, 2023).
Watson syndrome (6 papers, 2016 to 2023). Watson syndrome is believed to be a variant of neurofibromatosis type 1. "Different pathogenic variants of NF1 gene may cause allelic disorders such as NF1, Watson syndrome (WS) and NFNS1." (PMID 36803953, 2023). "NFNS and Watson syndrome (MIM 193520) exhibit a higher prevalence of non-truncating variants in NF1 (exons 24 and 25) and are two phenotypic subtypes of NF1." (PMID 36831560, 2023). "Similarly, an increased proportion of missense/in-frame mutations in individuals with NF1-related PVS, most of whom clinically fit with NFNS or Watson syndrome (WTSN #193520), an NF1-related trait with PVS, CaLS, and intelligence at the lower end of the normal change, was reported." (PMID 31487937, 2019).
Wilms tumor (6 papers, 2007 to 2025). An embryonal neoplasm characterized by the presence of epithelial, mesenchymal, and blastema components. "VUS were also detected in NF1 in a patient without clinical symptoms of NF1, BRCA2 in a patient with nephroblastoma, SMARCA4 in a patient with Ewing sarcoma, and SEC23B, a candidate gene for Cowden, in a patient with multiple tumours and an additional pathogenic heterozygous RECQL4 variant." (PMID 37507557, 2023).
acromegaly (5 papers, 2020 to 2025). Acromegaly is an acquired disorder related to excessive production of growth hormone (GH) and characterized by progressive somatic disfigurement (mainly involving the face and extremities) and systemic manifestations. "Growth hormone excess in association with optic glioma and germline NF1 variants has been reported, but a pathogenic role for NF1 and RET germline variants is yet to be elucidated in PitNETs." (PMID 35938916, 2022). "This was the first reported rare MEN1-like case of genetically diagnosed NF1 complicated with acromegaly caused by somatotroph adenoma." (PMID 33574795, 2020). "However, there are currently no data available regarding the molecular characteristics of NF1 forms associated with acromegaly." (PMID 39194755, 2024). "Syndromes associated with acromegaly include multiple endocrine neoplasia type 1 (MEN1) and type 4 (MEN4), Carney complex type 1 (CNC), McCune–Albright syndrome (MAS), the 3P association (3Pa), and neurofibromatosis type 1 (NF1)." (PMID 39194755, 2024). "A 52-year-old Caucasian male with NF1 diagnosed at the age of 36 after workup of a left adrenal pheochromocytoma and a non-functional pNET was presented for the evaluation of acromegaly." (PMID 35456261, 2022).
adrenal tumors (5 papers, 2014 to 2024). "The majority of NF1-associated PCC/PGL were benign unilateral adrenal tumors, which were biochemically active and positive on MIBG scans." (PMID 29977594, 2018). "Although, rare extra adrenal tumours can also be found in VHL, TMEM 127, NF1, and RET mutations as well." (PMID 29166454, 2017). "Considering the location of the tumour; intra-adrenal tumours suggest possible RET, VHL, NF1, TMEM 127, MAX or rarely KIF1B mutations." (PMID 29166454, 2017). "Contrary to experiences from Europe, Asian patients with PPGL due to PVs in kinase signaling genes NF1, HRAS, and FGFR1 showed a high proportion of sympathetic tumors, while European patients almost exclusively had adrenal tumors (P < .005)." (PMID 38481600, 2024).
autoimmune disease (5 papers, 2013 to 2021). A disorder resulting from loss of function or tissue destruction of an organ or multiple organs, arising from humoral or cellular immune responses of the individual to their own tissue constituents. "The number of studies reporting an association between NF1 and autoimmune disorders is small but increasing." (PMID 32973676, 2020). "As proof of principle, an association between some autoimmune diseases and NF1 has been reported, most likely as a result of enhanced immune function due to NF1 heterozygosity." (PMID 32439933, 2020). "The mechanisms underlying a possible association between autoimmune disorders and NF1 have not been elucidated." (PMID 32973676, 2020). "Nanda emphasised the relationship between NF1 and autoimmune diseases." (PMID 28552839, 2017). "As the number of reports on the coexistence of NF1 and autoimmune diseases increases, an association rather than a coincidence becomes more likely." (PMID 24286013, 2013).
brain glioma (5 papers, 2014 to 2024). A malignant glioma that involves the brain. "Four manifestations were rephrased, and for NF1, ‘brain or spinal cord glioma’ was split into three separate manifestations: low grade brain glioma, high grade brain glioma, and low grade spinal cord glioma." (PMID 33903738, 2021). "Other NF1-related manifestations were present only in a small number of participants: one participant had a history of OPG, one had a low grade non-OPG brain glioma and four had an osseous lesion." (PMID 38499890, 2024).